CGAS (cyclic GMP-AMP synthase)
Diseases named in the same sentence as CGAS in open-access papers (continued):
Sharing a sentence is not in itself a finding about the gene and the disease.
tumor (continued). "Recent studies have proved that radiotherapy treatment and the resulting anti-tumor efficacy is closely related to the activation of the cGAS-STING pathway and production of type I IFN." (PMID 35889509, 2022). "The reduction in the cGAS-STING response protects cancer cells from tumor rejection by CD8+ T cells." (PMID 35741087, 2022). "The cytosolic DNA can bind to cGAS to activate the cGAS-STING-type I IFN signaling in both tumor- and antigen-presenting cells." (PMID 36230769, 2022). "The cGAS-STING pathway, which senses cytosolic DNA, has been linked to an anti-tumor inflammatory response." (PMID 36624848, 2022). "MB21D2, a key enzyme involved in the cGAS/STING signaling pathway, is also frequently mutated in NSCLC and HNSCC to promote tumor progression." (PMID 35991889, 2022). "It is traditionally conceived that under this condition the constant activation of cGAS by the cytosolic DNA should suppress tumor development through the induction of tumor-opposing inflammatory response." (PMID 35992877, 2022). "Immunolabelling of cGAS and STING in metastatic CRC was performed and further complemented by histological classification, tumour grade, and KRAS, NRAS, and BRAF mutational status of mCRC." (PMID 36612217, 2022). "cGAS has been shown to act in a tumor suppressive manner through increased immune surveillance, promoting cell senescence, and contributing to apoptotic cell death in cancer cells." (PMID 36612150, 2022). "Together, these data show that mitotic SENP3 activates cGAS signaling-mediated innate immune response in tumor cells." (PMID 35869062, 2022). "We have shown that mitotic SENP3 activation increases abnormal mitosis-caused chromatin instability, which leads to nucleus DNA strands releasing into the cytoplasm and the formation of micronucleus in tumor cells to activate cGAS signaling." (PMID 35869062, 2022). "In this study, we showed that the mitotic SENP3 phosphorylation modulates host anti-tumor immunity by regulating MN-induced cGAS-STING signaling." (PMID 35869062, 2022). "cGAS-STING signaling acts at several levels in both tumor and immune cells for the generation of adaptive T cell responses." (PMID 36559204, 2022). "The results indicated that the Bio-MnO2 NPs not only relieved tumor hypoxia so as to augment the efficacy of RT, but also synergistically enhanced the cGAS-STING activity to activate radioimmune responses, boosting ICD while increasing CTLs infiltration." (PMID 36144927, 2022). "Overall, the analysis results on STING-KO mice collectively supported the crucial role of host cGAS-STING machineries in the nanoagonist-enabled tumor therapy." (PMID 36167857, 2022). "The sensing of cGAS to tumor-derived double-stranded DNA activates STING by generating cyclic GMP-AMP (cGAMP)." (PMID 36071479, 2022). "Taken together, these findings reveal that cGAS has a promoting effect on tumor growth by inhibiting HR-mediated DNA repair, revealing an innate immune-independent function of cGAS." (PMID 34374004, 2022). "During the mitotic arrest of tumor cells induced by anticancer drugs such as paclitaxel, cGAS prefers to bind to nucleosomes, which in turn activates the enzymatic activity to synthesize cGAMP." (PMID 35536585, 2022). "Nonetheless, recent studies have shown that ATM inhibitors can promote response to checkpoint immunotherapy through cGAS/STING signaling in tumor cells, resulting in an enhanced interferon I response and increased immunogenicity." (PMID 36353752, 2022). "The accumulation of tumor-derived DNA in the cytoplasm is recognized by the receptor cyclic GMP-AMP (cGAMP) synthase (cGAS), which induces the formation of a second messenger, cGAMP." (PMID 35292881, 2022). "The cGAS-STING pathway activation by tumor-derived DNA can induce cellular senescence, pro-inflammatory cytokine expression, and immuno-surveillance to suppress tumorigenesis by promoting the release of type I interferons (IFNs)." (PMID 35209954, 2022).
tumor (continued). "But how does dsDNA, a macromolecule shed by dead or dying tumor cells, end up in the cytosol of dendritic cells to activate the cGAS-STING pathway?" (PMID 35911757, 2022). "Recent evidence emerged on activating “cold tumor” to “hot tumor” through the restoration of cGAS/STING pathway to enhance immune-based therapy response." (PMID 35327359, 2022). "FMT from the R but not NR patients caused a significant delay in tumor growth after RT in the wild-type mice, but this tumor growth-suppressive effect disappeared in cGAS- and STING-knockout mice." (PMID 36093568, 2022). "To validate that osimertinib leads to cGAS activation and cGAMP production within tumor cells, we generated H1975 cells stably expressing a biosensor called BioSTING." (PMID 35347108, 2022). "In the tumor microenvironment, the immune surveillance mechanism of cGAS-STING has been well characterized and is mediated by infiltrating immune cells, such as dendric cells (DCs) and T cells, through type I IFN signaling." (PMID 36231006, 2022). "Tumor ablation by ionizing radiation is known to result in DNA damage leading to activation of the cGAS-STING pathway and thereby a type I interferon response." (PMID 36257966, 2022). "More comprehensive knowledge on the regulation of cGAS/STING signalling can availably harness anti‐tumour immunity following IR." (PMID 35415876, 2022). "It has been demonstrated that activation of the cGAS-STING pathway plays a dichotomous role in tumor development." (PMID 35209954, 2022). "Of note, olaparib-induced increase in terms of CD8+ T cell recruiting in the TME has been shown to be mediated by the tumor cGAS/STING pathway, an effect more obvious in HR-defective than in HR-proficient TNBC cells." (PMID 36428727, 2022). "Previously, cGAS-STING-TBK1 signaling pathway was reported to play a crucial role in the anti-tumor immunity." (PMID 35281267, 2022). "In this study, dual inhibition of H3K9me2 and H3K27me3 suppressed cGAS-STING signaling by decreasing CCF in tumor cells, thereby inhibiting the secretion of SASP." (PMID 35409271, 2022). "Previous studies have indicated that cGAS-STING signaling was correlated with DC in anti-tumor immunity." (PMID 36581992, 2022). "cGAS was found to inhibit the proliferation of normal and tumor cells, and this inhibition was dependent on its nuclear localization and DNA-binding ability, not on its enzymatic activity and downstream STING proteins." (PMID 35536585, 2022). "Consistently, the loss of Y211 phosphorylation induces the cGAS-STING cascade, leading to an anti-tumor inflammatory response." (PMID 35628489, 2022). "Tumor infiltrating antigen presenting cells (APCs) can sense tumor-derived cytosolic DNA via cyclic-GMP-AMP synthase (cGAS) which activates the protein STING." (PMID 35626062, 2022). "Meanwhile, DNA repair defects due to BRCA1/2 mutation instigate immune signaling through the cGAS/STING pathway, and the inflammatory signaling provides both tumor-suppressive as well as tumor-promoting traits." (PMID 36741696, 2022). "Dysregulation of cGAS results in intrusion of cellular homeostasis during viral or bacterial infections, creating a tumor-prone microenvironment by promoting evasion of immune surveillance." (PMID 36139387, 2022). "Recent studies have also demonstrated the role of cGAS–STING as a detector of neoplasm-induced processes." (PMID 35734577, 2022). "After the identification of cGAMP as the product of the dsDNA-mediated activation of cGAS, it was shown that this molecule had tumor suppressive activity in different preclinical tumor models." (PMID 35406723, 2022). "In cGAS-STING-defective tumour models, Wee1 inhibition can upregulate immune signalling through the dsRNA anti-viral defence pathway by promoting expression of endogenous retroviral element (ERV)." (PMID 36106115, 2022).
tumor (continued). "Conversely, overexpression of STING rescued cytokine production, indicating that the cGAS/STING pathway plays a key role in TTFields’ downstream effects in tumor cells." (PMID 35426370, 2022). "The tumor irradiation induces DNA damage, resulting in cGAS-STING pathway activation through sensing of cytosolic dsDNA fragments translocated to the cytoplasm." (PMID 35565217, 2022). "As one of the representative DDR-targeting agents, PARPis were confirmed to elicit tumor-antitumor immunity via the cGAS-STING pathway." (PMID 35626108, 2022). "And the loss of cGAS-mediated AIS decreased the regression of local and abscopal tumours in the context of focal IR and immune checkpoint blockade." (PMID 36402783, 2022). "Given that cytosolic DNA plays an important role in activating the cGAS-STING-type I IFN signaling in tumor cells, we utilized the production of cytosolic DNA as an index to screen candidate drugs for an enhancer of anit-PD-1." (PMID 36230769, 2022). "In vivo treatment with DDR inhibitors in combination with anti-PD-L1 leads to a strong anti-tumor effect in a cGAS–STING-dependent manner." (PMID 36359882, 2022). "The current study demonstrates that during RT-mediated ICD, tumor-derived dsDNA enters the cytoplasm of DCs and activates the cGAS-STING DNA-sensing pathway signaling a type-I IFN response in which TREX1 exerts an inhibitory effect by degrading DNA." (PMID 36532071, 2022). "STING downregulation in SCLC tumours also correlates with a lower expression of cGAS/STING pathway-dependent genes, for both NF-kB- and IRF3-related responses." (PMID 35794238, 2022). "Tumor mtDNA directly interacted with cGAS in the cytosol of DCs, sparking the cGAS-STING-IRF3 signaling pathway and eventually initiating IFN-β production and cross-prime CD8+ T cells." (PMID 35978433, 2022). "cGAS was found slightly upregulated only in LUAD tumour samples compared to normal tissues (2.511e-06) while TBK1 showed no significant expression changes between tumour and normal samples." (PMID 35794238, 2022). "The various aspects of BER dynamics to modulate the macrophages population that are present in high numbers in the tumor microenvironment (tumor-associated macrophage) and its role in how BER contributes to cGAS/STING inflammatory pathways is included." (PMID 35327359, 2022). "Studies on the relationship between cGAS/STING/TBK1 and distant metastasis of tumors have confirmed that the activation of cGAS/STING/TBK1 inhibits tumor metastasis by synthesizing IFN and recruiting NK cells and macrophages." (PMID 35844603, 2022). "Tumor-derived DNA activates the cGAS–STING pathway in tumor-infiltrating DC inducing type I IFN production upregulating CD8+-mediated antitumor activity." (PMID 36359882, 2022). "In multiple tumor types, the activation of cGAS is thought to inhibit tumor proliferation by activating the STING-dependent immune response, although this function is weakened due to the binding of nucleosomes." (PMID 36230972, 2022). "Further evidence suggests that the cGAS-STING signaling is important in the immune environment of various tumor microenvironments." (PMID 36359370, 2022). "DNA released from dying tumor cells stimulates the cyclic GMP-AMP synthase (cGAS)-stimulator of interferon genes protein (STING) pathway." (PMID 35806328, 2022). "Tumor cell-derived DNA activates the cGAS–STING pathway that induces T cell activation both in vivo and in vitro." (PMID 36235254, 2022). "Blockade of MERTK macrophage receptor increases tumor immunogenicity and potentiates antitumor immunity by inducing the tumor-cGAS- and host-STING-dependent type I interferon (IFN) response." (PMID 36216827, 2022). "The keywords of the hotspot include activation, STING pathway, cyclic GMP AMP, dendritic cell, I interferon, innate immunity, inflammation, cGAS, T cell, and tumor microenvironment." (PMID 36467504, 2022).
tumor (continued). "Meanwhile, myeloid-derived suppressor cells (MDSCs) were minor in D-positive samples, suggesting a strong association between the presence of cGAS-STING signaling and the tumor immune microenvironment (TIME)." (PMID 35773436, 2022). "As the key innate immune system receptors, TLRs and cGAS-STING are essential in controlling tumor development, progression, and relevant therapeutic outcomes." (PMID 36588690, 2022). "The involvement of DNA sensors in the antitumor response makes them attractive drug targets in tumor therapy, particularly for the cGAS-STING pathway and its downstream transcription factors IRF3 and NF-κB." (PMID 35983076, 2022). "Conversely, mtDNA released in response to stress in tumor cells induces autophagy-dependent ferroptosis through cGAS-STING signaling pathway activation." (PMID 35185917, 2022). "β-lapachone causes immunogenic tumor cell apoptosis and releases abundant dsDNA into TME, while Mn2+ enhances the sensitivity of cGAS to dsDNA and augments STING signaling to trigger downstream immunostimulatory signals." (PMID 36167857, 2022). "Subsequent studies have shown that the cGAS-STING signaling pathway is an important contributor to antitumor immunity after radiotherapy by detecting DNA damage in tumor cells and promoting the recognition of tumor-derived DNA in immune cells." (PMID 35185917, 2022). "The low death rate of BMDCs in response to Lap treatment suggests that the most of the dsDNAs in the post-treatment TME are originated from tumor cells and supports the tumor-specificity of the nanoagonist-stimulated cGAS-STING-mediated immunity." (PMID 36167857, 2022). "NBTXR3-mediated radiotherapy not only leads to enhanced direct tumor destruction, but also can activate the cGAS-STING pathway in cancer cells, improve the immunogenic cell death and modulate the immunopeptidome for promoting antitumor immunity." (PMID 36405757, 2022). "Another group showed that the cGAS/STING pathway in tumor cells contributes to T cell priming, and sensitizes tumor to checkpoint therapy." (PMID 35836810, 2022). "The most widely reported is TMEM173, known as STING, which participates in tumor immunity by regulating the natural immune response mediated by the cGAS-STING signaling pathway." (PMID 35392225, 2022). "IR-activated cGAS/STING upregulates the expression of PD-L1 in tumor cells that contributes to RT resistance and immune escape." (PMID 36443299, 2022). "Together, these data reveal that mitotic SENP3 activation in tumor cells can promote host anti-tumor immune response by coupling with cGAS signaling." (PMID 35869062, 2022). "The infiltration levels of CD8+ T cells in tumor tissues were recently proven to be consistent with the functional cGAS-STING pathway." (PMID 36230972, 2022). "ONP-302 infusion decreased tumor growth via the activation of the cGAS/STING pathway within myeloid cells, and subsequently increased NK cell activation via an IL-15-dependent mechanism." (PMID 36059473, 2022). "The current study employs patient-derived tumor organoids (PDTOs) to test the combined inhibition of cGAS-STING and EGFR." (PMID 35992877, 2022). "Activation of the cGAS-STING pathway can induce the recruitment of immune cells into the tumor microenvironment, such as CD8+ T cells, dendritic cells (DCs), and natural killer (NK) cells." (PMID 35983076, 2022). "The inhibition of ENPP1 differs from the pharmacologic activation of STING in a few crucial ways, even though they all elicit anti-tumor immunity through the cGAS-STING-TBK1-IRF3 signaling pathway." (PMID 35806118, 2022). "Our group recently used zebularine (a demethylating agent) to activate the cGAS-STING signaling pathway in tumor cells." (PMID 35185917, 2022). "Based on previous research, the effective range of cGAS-STING has been extended to include all aspects of resistance to infection by pathogenic microorganisms (bacteria, viruses, parasites), anti-tumor, fibrosis, immunity, and inflammation." (PMID 36545321, 2022).
tumor (continued). "Loss of cGAS-mediated AIS decreased the regression of local and abscopal tumours in the context of focal radiation and immune checkpoint blockade." (PMID 36402783, 2022). "A previous study reported that the cGAS/STING pathway in dendritic cells mediated sensing of irradiated-tumor cells and enhanced adaptive immune responses to radiation." (PMID 35836810, 2022). "Some recent studies show that CIN is also involved in the crosstalk between a tumor and its surrounding microenvironment, which is mediated by the cGAS-STING pathway." (PMID 34374004, 2022). "Lastly, we demonstrate that ONP-302-induced regulation of tumor growth is initiated by uptake of the nanoparticles by myeloid cells which induces the activation of the cGAS/STING pathway." (PMID 36059473, 2022). "Using STING- (Tmem173−/−) and cGAS-knockout (Mb21d1–/–) mouse tumor models, we confirmed that the gut microbiome regulates RT sensitivity in HCC via cGAS–STING signaling in dendritic cells (DCs), which in turn, modulate host cytotoxic T lymphocyte responses." (PMID 36093568, 2022). "By evaluating the tumor levels of cGAS and STING with IHC in a large cohort retrospective study (n = 259), we found lower expression levels of cGAS and STING in patients with CRC (n = 259)." (PMID 35835756, 2022). "These combined results confirmed that osimertinib activates cGAS in tumor cells to produce cGAMP, promoting surrounding macrophages to increase STING-mediated type-I IFN responses." (PMID 35347108, 2022). "It is thought that STING agonists mimic tumor-derived DNA, which can bind to cGAS in the cytoplasm of APCs, initiating a Type 1 IFN response." (PMID 36551577, 2022). "It has been established that the cGAS–STING pathway plays a major role in inhibiting tumor growth by upregulating T cell response." (PMID 36235254, 2022). "Further studies are also needed to determine the mechanisms of directing the cGAS-STING activation to anti- or pro-tumor autophagic flux." (PMID 35992877, 2022). "The subsequent triggering of the cGAS-STING pathway in the dendritic cells leads to robust anti-tumor immunity." (PMID 35911757, 2022). "Recent studies have performed that the cGAS/STING pathway is activated in APC via free DNA in tumor, which renders tumor vulnerable to immunological surveillance." (PMID 35265630, 2021). "The cGAS–STING pathway truly has a very important role not only in anti-tumor immunity but also in immune links to other diseases." (PMID 34906241, 2021). "In conclusion, the cGAS-STING signaling pathway is critically involved in tumor immune escape and has great inspiration for cancer treatment." (PMID 34483930, 2021). "Cytosolic tumor-derived dsDNA is sensed by cyclic GMP-AMP synthase (cGAS) to generate cGAMP required for the activation of stimulator of interferon genes (STING), resulting in the production of interferon-β and induction of several interferon-stimulated genes." (PMID 34386508, 2021). "Treatment of mice after HCC development with 3′3′-cAIMP, a cyclic dinucleotide STING agonist, effectively reduces the tumor size in cGAS–/– mice, which cannot generate 2′3′-cGAMP." (PMID 34386500, 2021). "In this context, the engagement of the cytosolic cGAS-STING signaling pathway seems to be essential for the establishment of such important tumor-suppressive program." (PMID 34571733, 2021). "To investigate if cGAS binds cytosolic DNA in tumor cells, we first co-labelled tumor cells for cGAS and different cytosolic DNA species." (PMID 33790360, 2021). "Beyond stimulating T cell proliferation, activation of the cGAS-STING pathway causes tumor vascular collapse and contributes to tumor cell death and apoptosis, promoting the release of tumor-associated antigens." (PMID 34016129, 2021). "Activation of the cGAS-STING pathway remodels the immune response to create a more susceptible TME which boosts immune priming and induces extrinsic tumour suppression." (PMID 34572747, 2021).